PRL (prolactin)
Diseases named in the same sentence as PRL in open-access papers (continued):
Sharing a sentence is not in itself a finding about the gene and the disease.
breast cancer (continued). "PRL was also able to enhance 17β-Estradiol (E2) dependent proliferation of breast cancer cells." (PMID 23758962, 2013). "Furthermore, gene ontology (GO) analysis based on PRL-upregulated genes demonstrated a concentration in homeostasis pathways, consistent with the known pro-differentiation role of PRL in breast cancer." (PMID 23758962, 2013). "Although pHe lower than 6.5 rarely occurs in extracellular space of solid tumors, it has remained unclear, based on limited in vitro experiments, whether such moderate extracellular acidosis of the microenvironment of breast cancer affects prolactin signaling." (PMID 24004716, 2013). "Moderate extracellular acidosis effectively blocks prolactin signaling in breast cancer." (PMID 24004716, 2013). "High serum prolactin (PRL) levels have been reported in pre-menopausal females with breast cancer and circulating PRL levels are positively correlated with the risk of breast cancer." (PMID 24137476, 2013). "We propose that acidosis-induced prolactin resistance represents a previously unrecognized mechanism by which breast cancer cells may escape homeostatic control." (PMID 24004716, 2013). "On the other hand, PRL may also exert pro-differentiation effects and act to suppress invasive features of established breast cancer." (PMID 23758962, 2013). "Some authors have reported that PRL promotes cell proliferation in some breast cancer cell lines." (PMID 24148306, 2013). "Considering the established role for AREG as a paracrine mediator of E2-induced proliferation of luminal breast epithelial cells during pubertal growth, AREG may be directly involved in PRL stimulation of E2-driven growth of human breast cancer." (PMID 23758962, 2013). "In addition, proliferation-regulation and negative regulation of apoptosis were also identified, which is consistent with the reported role of PRL contributing to breast cancer initiation and growth." (PMID 23758962, 2013). "In vivo studies showed that high levels of PRL accelerated the emergence of spontaneous mammary tumors and could act as an anti-cytotoxic factor in breast cancer cells, contributing to drug resistance." (PMID 23317095, 2013). "Thus, under acidic conditions that completely blocked prolactin-induced signaling, breast cancer cells remained viable and fully capable of responding to other extracellular factors." (PMID 24004716, 2013). "In summary, the prolactin-Jak2-Stat5 pathway, which may suppress breast cancer cell epithelial-to-mesenchymal transition, invasion and drug resistance, is potently and selectively suppressed by extracellular tumor acidosis." (PMID 24004716, 2013). "Interestingly, an elegant study from the Ali laboratory, revealed prolactin to also act as a suppressor of metastasis in breast cancer." (PMID 27340590, 2012). "Furthermore, prolactin-suppression of the Bcl6 oncogene in human breast cancer cell lines was preferentially mediated by Stat5a over Stat5b." (PMID 23036105, 2012). "Also were serum and tissue homogenate levels of PRL found to be elevated in dogs with benign and malignant mammary tumors." (PMID 22647582, 2012). "There is a growing body of epidemiologic evidence supporting an association between circulating prolactin levels and breast cancer risk, although data are not conclusive." (PMID 21470416, 2011). "Few studies have investigated the association between SNPs in PRL and PRLR and breast cancer risk." (PMID 21470416, 2011). "As PRL mediates its effects via, among others, JAK2/STAT5 signaling in breast cancer cells, this could provide a means by which PRL could directly activate PPARα transcription independent from LKB1 and AMPK." (PMID 21294903, 2011). "The current study examined breast cancer as a metabolic disease in the context of altered fatty acid catabolism by examining the effect of PRL on carnitine palmitoyl transferase 1 (CPT1), an enzyme that shuttles long-chain fatty acids into the mitochondrial matrix for β-oxidation." (PMID 21294903, 2011).
breast cancer (continued). "Similarly, in a breast cancer cell line induced to endogenously produce high levels of prolactin, proliferation was magnified by the addition of estradiol." (PMID 22017816, 2011). "We therefore examined whether PRL could have differential effects on fatty acid catabolism in breast cancer cells." (PMID 21294903, 2011). "Previous data have suggested that a positive family history of breast cancer may be related to higher PRL levels, especially among premenopausal women." (PMID 20736944, 2010). "These insights may prove important in the treatment of breast cancer and other PRL responsive diseases." (PMID 21144038, 2010). "The role of prolactin (PRL) in human breast cancer is now becoming more clearly defined." (PMID 21144038, 2010). "Accordingly, continued study of the importance of PRL in breast cancer is warranted." (PMID 20736944, 2010). "Recent evidence indicates that high levels of PRL in blood imparts increased risk of developing breast cancer, independent of other risk factors." (PMID 21144038, 2010). "Notably, our case–control results must be interpreted with caution as PRL is a stress hormone and we cannot exclude that the relationship with breast cancer was influenced by a stress responses." (PMID 20736944, 2010). "A recent analysis of women from the Nurses’ Health Study (NHS) I and II found that higher PRL levels were associated with breast cancer risk, irrespective of menopausal status (RR=1.3, 95% confidence interval (CI) 1.1–1.6, Phet=0.95)." (PMID 20736944, 2010). "Importantly, a recent study investigating the effects of STAT5a on breast cancer cell migration and invasion showed that prolactin (Prl)-induced activation of STAT5a inhibited migration and invasion of BT-20 and T-47D human breast cancer cells." (PMID 19630967, 2009). "During pregnancy, high concentrations of oestrogen, progesterone and prolactin promote the growth of ducts and the formation of tubuloalveolar structures; progesterone and prolactin are known for their synergistic proliferative activity, playing a defined role in murine and human breast cancer." (PMID 19183446, 2009). "This identifies one mechanism by which prolactin contributes to breast cancer." (PMID 19014541, 2008). "In our study, pGL4-CISH reporter demonstrated a 2-fold induction upon 1 ng/ml of PRL treatment, suggesting this reporter was significantly more sensitive than the thymidine-incorporated proliferation assay to detect breast cancer cell responsiveness to PRL stimulation." (PMID 18254957, 2008). "However, in breast cancer cells these existing reporter constructs have proven to be relatively insensitive to the effects of PRL, requiring supra-physiologic concentrations of PRL (>200 ng/ml) to detect reporter induction." (PMID 18254957, 2008). "Coexpression of the PRLR in breast cancer cells suggests that such prolactin may act in an autocrine/paracrine fashion to influence cell growth and survival." (PMID 18681966, 2008). "Furthermore, breast cancer cell lines engineered to overexpress autocrine prolactin are resistant to taxane-mediated cell death both in vitro and in tumour xenografts in vivo." (PMID 18681966, 2008). "Cloning of the promoter region of the CISH gene into the improved pGL4.10 luciferase reporter construct resulted in a highly sensitive, PRL-responsive reporter that should be of widespread utility in examining PRL/Stat5 pathway in ER+ human breast cancer cells." (PMID 18254957, 2008). "Moreover, multiple breast cancer cell lines have been shown to synthesise and secrete bioactive prolactin in vitro." (PMID 18681966, 2008). "Prolactin signalling has been implicated in each of these phenomena in breast cancer cells though its role in drug resistance has not yet been thoroughly examined." (PMID 19014541, 2008). "However, prolactin is produced in an autocrine and/or paracrine manner by breast cancer cells and normal breast cells, and it is said that its activity is expressed only at the cellular level." (PMID 17543123, 2007).
breast cancer (continued). "The increase of blood PRL levels in NMU-induced rats may be an indicator of a poor prognosis of mammary cancer evolution." (PMID 18045456, 2007). "PRL may act as a positive growth factor in mammary tumour development and increase the proliferation of breast cancer cells in rats." (PMID 18045456, 2007). "No haplotypes in PRL or PRLR haplotypes were significantly associated with breast cancer risk using our type I error criteria (p < 0.0005)." (PMID 18053149, 2007). "However, PRL is also synthesized and secreted by a broad range of cells, including those of the immune system, breast cancers, and the lining of the pregnant uterus." (PMID 15811834, 2005). "This study demonstrated that prolactin protects human breast cancer cell lines against apoptosis and this may have important implications for cancer treatment." (PMID 15213724, 2004). "In addition, we found that the levels of endogenous prolactin made by the breast cancer cell lines appeared to correlate with their sensitivity to a physiological inducer of apoptosis, C2-ceramide." (PMID 15213724, 2004). "However, levels of PRL in plasma were significantly lower in our treated patients with primary operable breast cancer relative to normal controls." (PMID 12698200, 2003). "Moreover, autocrine production of GH in human mammary cell lines promotes the transformed phenotype, and prolactin increases the motility of breast cancer lines." (PMID 12888825, 2003). "Recent studies have shown the importance of autocrine/paracrine production of hGH and hPRL during human breast carcinoma cell proliferation in vitro and have proposed that local production of PRL in vivo is more important than systemic PRL for the tumour formation." (PMID 12888825, 2003). "A further study in the NHS found higher blood levels of prolactin to be associated with an increased risk of breast cancer in postmenopausal, but not in premenopausal women." (PMID 12373602, 2002). "Having shown that PRL is a polarity cue in MECs, therefore, we investigated whether PRL may regulate acini morphogenesis in breast cancer cells representative of the different breast cancer subtypes when cultivated in our 3D-cell culture model." (PMID 40157909, 2025). "Having shown that PRL/PRLR pathway regulates Hippo/YAP pathway in breast cancer cells, we next wished to determine whether PRL signaling also exerts a regulatory role on the Hippo pathway in MECs and whether this regulation is linked to PRL-mediated mammary acini morphogenesis." (PMID 40157909, 2025). "Severe HPRL necessitates intervention regardless of symptomatology due to established associations with accelerated osteoporosis and cardiovascular morbidity, and studies have also suggested that there may be a correlation between PRL levels and the occurrence of breast cancer." (PMID 40964426, 2025). "Also, PRL/PRLR is expressed in 95% of mammary tumors and 60% of male breast carcinomas." (PMID 40160874, 2025). "However, some studies have shown that there is an association between the use of antipsychotic drugs that increase prolactin levels and an increased risk of breast cancer in women, although the causal relationship has not been established." (PMID 40465597, 2025). "However, recent evidence does not support the association between SSRIs and the risk of breast cancer, and a recent cohort study did not observe increased prolactin levels among women using antidepressants or SSRIs." (PMID 38554178, 2025). "On the basis of the observation that, in several immunohistochemical studies of patients with breast carcinoma, PRLr is expressed at high levels, the evaluation of PRLr expression should be considered in these patients and should be mandatory in patients diagnosed with PRL-secreting PitNETs." (PMID 40160874, 2025).
breast cancer (continued). "The results of our three-method MR analysis concluded that antidepressant medication did not increase the risk of breast cancer, and that although prolactin levels were associated with breast cancer, there was no causal relationship between SSRI use and prolactin levels." (PMID 37540479, 2024). "The possible link between prolactin levels and breast cancer has led to a concern regarding the use of antipsychotic drugs, including first generation antipsychotics and some second generation medications, because of the known effect of these agents to increase prolactin levels." (PMID 38595824, 2024). "The hypothesis was that a similar association between breast cancer and exposure to prolactin-increasing, but not to prolactin-sparing antipsychotics, would be found." (PMID 38687213, 2024). "In a prior analysis in the Nurses’ Health Study (NHS) and NHSII we observed that plasma prolactin levels greater than 11 ng/mL measured within 10 years of diagnosis were associated with a greater risk of breast cancer among postmenopausal, but not premenopausal, women." (PMID 36882838, 2023). "There were evidences that prolactin levels were associated with breast cancer risk, regardless of whether the patient was pre-or post-menopausal." (PMID 37448488, 2023). "Also, these results indicate that PRL role in breast cancer needs further evaluation." (PMID 36157462, 2022). "The potent crosstalk of PRL with growth factor-initiated signals observed both in breast cancer cell lines, and anti-estrogen resistant ER+ PDXs has suggested that targeting PRL signaling in combination with these pathways may be an efficacious therapeutic strategy." (PMID 35784527, 2022). "In addition, studies of patients with conditions that result in high circulating PRL levels such as prolactinomas or the use of antipsychotics showed no causal link to breast cancer." (PMID 36157462, 2022). "Recently, scientists have focused on the role of the prolactin receptors (PRL-R) and serum prolactin (PRL) in the carcinogenesis, prognosis, and metastasis of breast cancer (BC)." (PMID 34945164, 2021). "PRL may be a potential marker for diagnosis of HER2+ breast cancer." (PMID 34099636, 2021). "Our data suggest the inhibition of mammary tumors by cumin bioactives could be due to the reversal of E2-mediated modulations in cell proliferation and E2-related markers, including the reduction in circulating prolactin levels." (PMID 34201250, 2021). "Therefore, inhibiting PRL can enhance the sensitivity of breast cancer cells to drugs." (PMID 34651424, 2021). "Moreover, many studies revealed that SHC1 participated in signalling through epidermal growth factor receptor‐2 (HER‐2), oestrogen receptor (ER) and prolactin (PR) signalling, which were well‐recognized biological markers for predicting prognosis and response to breast cancer therapy." (PMID 34117717, 2021). "PRL inhibitor bromocriptine (Br) could mitigate OXTR-driven mammary tumor growth." (PMID 34099636, 2021). "In addition, Br is an effective antitumor drug for OXTR/PRL-driven HER2+ breast cancer." (PMID 34099636, 2021). "In addition, CAML is essential in the growth of PRL/PRLR‐dependent breast cancer cells." (PMID 34651424, 2021). "In addition, prolactin promotes breast cancer bone metastasis." (PMID 34226298, 2021). "Epidemiologic studies are lacking on pregnancy prolactin concentrations and breast cancer risk, but the higher levels in Mongolian women could indicate a possible protective effect for breast cancer." (PMID 32012981, 2020). "However, how the close functioning of the progesterone/PR and prolactin/PRLR signaling axes that drive the lactogenic/lipogenic phenotypic outcomes in normal mammary gland might be altered in breast cancer tissues remains largely unexplored." (PMID 33335078, 2020).
breast cancer (continued). "In order to assess whether PRL-induced tyrosyl phosphorylation of PAK1 has a physiological effect on breast cancer metastasis, TMX2-28 stably overexpressing GFP, myc-PAK1 WT, or myc-PAK1 Y3F were inoculated in mouse mammary fat pads and mice were treated with PRL for 8 weeks." (PMID 27542844, 2016). "Prolactin has normal bone homeostatic roles and, combined with the natural “recycling” of proteins in different tissues that can be used for breast development and function, or in bone function, increases the impact of prolactin signaling in breast cancer bone metastases." (PMID 27782069, 2016). "In addition, our analysis revealed a positive association between plasma prolactin levels and the risk of breast cancer in patients who were positive for ER+/PR+, but not for the other ER/PR status." (PMID 27184120, 2016). "Due to the paucity of relevant publications, we were not able to assess whether the rhythm of prolactin levels is correlated with the risk of breast cancer in the present study." (PMID 27184120, 2016). "Finally, because molecular modeling showed that the Asp-426 side chain in CNNM3 buries into the catalytic cavity of PRL-2, we showed that a PRL inhibitor could abrogate complex formation, resulting in a decrease in proliferation of human breast cancer cells." (PMID 26969161, 2016). "Interestingly, breast cancer cells secrete bone modulating factors most likely because they are produced normally in the breast for breast developmental processes: a number of these factors are PRL-regulated." (PMID 27782069, 2016). "Indeed, no previous studies have reported how various forms of prolactin differentially influence the risk of breast cancer development." (PMID 27184120, 2016). "Based on our results, it may be hypothesized that some of the effects of PRL on breast cancer cell motility may be triggered through recruitment of the small adapter protein, c-Src, and to FAK and moesin recruitment, followed by actin rearrangement and enhancement of cell motility." (PMID 26733941, 2015). "To begin to assess the clinical relevance of the newly identified PRL-modulated transcripts, we selected the gene product most strongly upregulated by PRL in the in vivo xenotransplant tumors, PTHrP, for protein expression analysis in clinical breast cancer specimens." (PMID 23758962, 2013). "Several studies have documented the involvement of the ligand PRL in the growth control of different tumors such as breast, liver and prostate and further, PRL antagonists such as hPRL-G129R has been demonstrated to inhibit breast cancer growth in vitro and in vivo." (PMID 24257371, 2013). "The new observations identify acidosis as a significant contributor to loss of Nuc-pYStat5 in clinical breast cancer specimens, and implicate acidosis-induced prolactin resistance as a previously unrecognized mechanism by which breast cancer cells may evade homeostatic control." (PMID 24004716, 2013). "Prolactin and prolactin receptors are present in normal breast tissue, benign breast disease, breast cancer cell lines, and breast tumor tissue, leading to speculation that the proliferative and antiapoptotic effects of prolactin in breast epithelial cells could be a factor in breast carcinogenesis." (PMID 21470416, 2011). "Additionally, we examined the association between PRL and PRLR SNPs and serum prolactin levels among controls, hypothesizing that altered serum prolactin levels may be an intermediate marker between genetic variation in PRL and PRLR and breast cancer risk." (PMID 21470416, 2011). "Exploration of genetic variants in PRL and PRLR has identified single-nucleotide polymorphisms (SNPs) that alter transcription factor binding, modify prolactin receptor activity, and may be associated with breast cancer risk or circulating prolactin levels." (PMID 21470416, 2011).